PDC (phosducin)
Diseases named in the same sentence as PDC in open-access papers (continued):
Sharing a sentence is not in itself a finding about the gene and the disease.
lupus (continued). "These recent studies had provided direct evidence of pDC involvement in development of autoimmune diseases like lupus." (PMID 27112985, 2016). "Two additional studies that selectively deplete pDC or abrogate IFNα-producing ability of pDC in lupus-prone mouse models other than MRL/lpr further demonstrate the importance of pDC in lupus pathogenesis." (PMID 27034965, 2016). "The second question is which TLR, TLR9, or TLR7 is critical for the role of pDC in lupus pathogenesis." (PMID 27034965, 2016). "In BXD2 lupus-prone mice, it was demonstrated that the accumulation of activated pDC in the MZ of spleen resulted in the upregulation of CD86 on MZ B cells, which was important for germinal center (GC) formation and autoantibody production." (PMID 27034965, 2016). "The enhanced PARs signaling pathway suggested that the activation of intestinal pDC might also be involved in the pathogenesis of lupus." (PMID 39871323, 2025). "Consequently, in murine models of lupus, reducing pDC levels improves the disease, and genetically compromised pDC function leads to disease improvement." (PMID 39737176, 2024). "Taken together, low ROS production due to NCF1 deficiency enhances AKT/mTOR-dependent pDC generation and promotes pDC migration via CCR2, which may explain the accumulation of pDCs during lupus." (PMID 36853827, 2023). "In lupus, the continuous deposition of circulating immune complexes induce ongoing pDC activation." (PMID 36633910, 2023). "Apart from myelopoiesis, enhanced cellular migration may also contribute to pDC accumulation during lupus." (PMID 36853827, 2023). "Therefore, we will next summarize in detail how cDC and pDC, respectively, break down immune tolerance to self and facilitate lupus progression." (PMID 27034965, 2016). "These depletion studies indicate the importance of cDC and pDC in the development of lupus." (PMID 27034965, 2016). "Based on the reviewed studies above, we summarize how cDC and pDC may be involved in lupus pathogenesis." (PMID 27034965, 2016). "In conclusion, pDC are activated alone with disease development and its phenotype and function differ among lupus-prone strains, and these differences may contribute to the development of lupus in these mice." (PMID 26879679, 2016). "One of the important functions of pDC is to present antigen and elicit subsequent T cell activation and this function maybe enhanced in lupus-prone mice." (PMID 26879679, 2016). "Effects of pDC depletion in different spontaneous lupus models." (PMID 26528288, 2015). "Furthermore, NETs have been shown to activate platelets which induce thrombosis at the site of vascular injury and induce IFNα production by pDC which are activated by NETs-stimulated lupus neutrophils." (PMID 24790989, 2014). "pDC have also been reported to contribute to autoimmune diseases, in this case, Systemic lupus erythematosus (SLE), Systemic Sclerosis or type I diabetes." (PMID 39483484, 2024). "Despite its potential as a probiotic through its anti-inflammatory and Treg-inducing properties, the increased growth of L. reuteri has the potential for translocation, which may induce the pathogenesis of lupus related to organ pathology and pDC/IFN triggering properties." (PMID 36624775, 2022). "Additionally, it is crucial to recognize that the manipulation of chemokines or their receptors may potentially exacerbate pDC-induced pathologies, including psoriasis and systemic lupus erythematosus." (PMID 35943802, 2022). "Indeed, pDC depletion showed a positive clinical impact in a mouse lupus model." (PMID 28181493, 2017). "However, only the depletion of pDC or blockade of IFNα signaling at early stage of disease could prevent lupus development." (PMID 27034965, 2016). "It is therefore not possible to confirm whether the pDC changes were a result of the underlying disease or that of the various lupus medications." (PMID 20618924, 2010).
lupus (continued). "In lupus-prone mice, pDC depletion mitigates disease severity, and in humans, administration of an anti-BDCA2 antibody—selectively inhibiting pDC function—significantly attenuates the peripheral IFN-I signature." (PMID 41301504, 2025). "Our results demonstrate that moderate decrease in ROS production in Ncf1R90/90H mice specifically promotes pDC accumulation and resultant type I IFN activation at an early stage of lupus." (PMID 36853827, 2023). "Clostridiales can ferment RS into short-chain fatty acids (SCFAs), thereby inhibiting the pathogenesis of lupus by decreasing IFN-I signalling and pDC." (PMID 36624775, 2022). "As in lupus, high abundance of IFN-α and pDC leads to BCR response, B cell proliferation, and antibody production and subsequent proteinuria in lupus." (PMID 29403161, 2017). "pDC and its secreted cytokine IFN-α in autoimmune diseases such as systemic lupus erythematosus and psoriasis have been addressed for their roles in eliciting inflammatory response and tissue damage." (PMID 29403161, 2017). "Our study herein found that pDC activation markers, including MHC-II molecules, CD80, IFNα and IFN signature, were upregulated in lupus-prone mice at the advanced lupus stage, thereby indicating that pDCs were activated and released IFNα in lupus-prone mice." (PMID 26879679, 2016). "In MRL/lpr lupus-prone mice, UVB irradiation induces skin infiltration of pDC, while IFNα response in the skin has been shown to be positively correlated with the level of chemerin that can attract pDC through chemR23." (PMID 27034965, 2016). "pDC can also accumulate in the skin of SLE patients and lupus-prone mice." (PMID 27034965, 2016). "Thus, infections could be a trigger of IFNα production by pDC in lupus." (PMID 27034965, 2016). "Given the predominant role of the pDC-IFN-I pathway in the early stages of lupus development, IFN-I and pDC blockade should be administrated to patients with relatively low disease scores." (PMID 26528288, 2015). "Thus, it is quite rational to consider this epicutaneous TLR7-inducible phenotype, which is pDC-dependent and partially IFN-dependent, as a viable lupus animal model." (PMID 31998321, 2019). "Overall, these data suggested that in vitro pDC development from BM cells was not grossly affected by the development of lupus." (PMID 27509492, 2016). "In MRL/lpr lupus-prone mice, constitutive depletion of cDC and pDC did not influence the negative selection of T cells in the thymus." (PMID 27034965, 2016). "Interestingly, pDC functional impairment has been described in systemic lupus erythematosus (SLE), a fact sometimes used to assert their lack of importance for this disease." (PMID 39920132, 2025). "Considering the fact that pDC-IFN-α blockade therapeutics including anti-IFN-α antibody, anti-IFNAR, pDC inhibitors, and TLR9 antagonist are in clinical trials with promising results in lupus, controlling the pDC-IFN-α axis may also have a beneficial effect for the treatment of IgA nephropathy." (PMID 29403161, 2017). "In mice, however, one study showed no change of pDC in the kidney as lupus progressed." (PMID 27034965, 2016). "However, pDC infiltration in the kidney was not detectable in the pre-lupus stage, whereas the renal pDC numbers were slightly increased in response to disease development in all tested strains." (PMID 26879679, 2016). "Depletion studies of whole DC populations, including both cDC and pDC, in MRL/lpr lupus-prone mice suggest the involvement of DC in promoting lupus development, but not activation of naïve T cells." (PMID 27034965, 2016). "It is possible that pDC in SLE patients and lupus-prone mice can still produce a normal level of IFNα through the TLR7 pathway." (PMID 27034965, 2016). "Thus, control of dysregulated pDC activation and type I IFN production provide an alternative treatment strategy for autoimmune diseases in which type I IFNs are elevated, such as systemic lupus erythematosus (SLE)." (PMID 20470398, 2010).
melanoma (24 papers, 2012 to 2025). A malignant, usually aggressive tumor composed of atypical, neoplastic melanocytes. "On the other hand, the histological regression of melanocytic lesions has been associated with dense pDC infiltration and MxA expression (particularly in thin regressive melanomas), as indicator of endogenous I-IFN production." (PMID 32054102, 2020). "On the other hand, CD123+ pDC that do in principle possess the capacity to promote antitumor responses are found to be associated with early relapse and poor prognosis in human melanoma." (PMID 29276510, 2017). "Remarkably, CCL17, CCL22, and matrix metalloproteinase-2 found in the melanoma microenvironment have been shown to be associated with pDC accumulation." (PMID 29085361, 2017). "However, the loss of PDC selectivity for melanoma cells compared to the carrier PDIP peptide needs to be addressed when designing future PDCs, especially when the cargo is a cell‐permeable, cytotoxic drug." (PMID 39834140, 2025). "However, published data indicate that melanoma-associated escape mechanisms are in place to hijack pDC functions." (PMID 32054102, 2020). "Also, there are sporadic reports of selective pDC efficacy, as is the case for intranodal injection of pDCs loaded with tumor-associated peptides in stage IV melanoma patients." (PMID 30987228, 2019). "This may indicate that melanoma-derived PGE2 exerts an inhibitory effect on IFN-I production by tumor-associated pDC, thus altering the downstream gene signature." (PMID 30979057, 2019). "pDC infiltration is strongly associated with primary melanoma cell expression of activated signal transducer and activator of transcription 3, which is constitutively expressed in cancer and is thought to be a significant mediator of tumor-induced immunosuppression." (PMID 29085361, 2017). "In the last decade, several trials have evaluated autologous pDC and cDC2 vaccines in metastatic melanoma patients, as well as in combination (both pDC and cDC2 vaccination) for stage 3 melanoma and prostate cancer." (PMID 38903502, 2024). "Our data is in line with data from melanoma patients, where pDC is shown to be increased in TDLN, and were demonstrated to correlate with poor prognosis." (PMID 38954023, 2024). "Stiffness–dependent cDC and pDC polarization also emerged in murine 3D co–cultures with melanoma cells, while both populations decreased in colon and breast cancer co–cultures." (PMID 39211033, 2024). "Melanoma-derived immunosuppressive cytokines and a metabolic drift represent relevant mechanisms enforcing pDC-mediated melanoma escape." (PMID 38239354, 2023). "Previous studies have shown that circulating pDC levels were decreased in blood of melanoma patients, however, pDCs were increased in primary tumors and tumor-draining lymph nodes, and pDC infiltration was associated with poor prognosis and early relapse." (PMID 34737750, 2021). "In recent years, different approaches have emerged for the treatment of melanoma that affect pDC functions." (PMID 34737750, 2021). "pDC infiltration predicts poor prognosis in PCM and is strongly associated with phospho-STAT3 expression by melanoma cells, suggesting a tumor-induced immunosuppression mechanism." (PMID 32054102, 2020). "We have recently reported that pDC recruitment is recurrent in the early phases of melanoma, but the entire pDC compartment collapses over melanoma progression." (PMID 32054102, 2020). "An increased pDC infiltration has been associated with poor outcome in breast cancer, ovarian cancer, NSCLC, OSCC and melanoma." (PMID 32054102, 2020). "The role of TLR7 or IFNAR signaling in pDC-mediated cytotoxicity was confirmed by using mouse models of melanoma." (PMID 32054102, 2020). "Here, we summarize recent advances on pDC biology and function within the context of melanoma immunity." (PMID 32054102, 2020).
melanoma (continued). "High numbers of pDC are present in skin lesions and draining lymph nodes of melanoma patients and in breast tumor biopsies, with a strong correlation between the presence of pDC and tumor aggressiveness, poor clinical outcomes and shorter survival." (PMID 30979057, 2019). "Recently, the recruitment of pDC to mouse melanoma lesions was reported upon exposure to human ß-defensin-expressing vaccinia virus." (PMID 31083559, 2019). "Depletion of pDC/cDC2 represents a well-known immune escape mechanism in several cancer entities such as melanoma and breast cancer." (PMID 30054667, 2018). "On the opposite, pDC are essentially involved in protective anti-viral immunity, priming of melanoma-specific CD8+ T cells and the pathogenesis of several diseases." (PMID 22952871, 2012). "Additionally, pDC function is impaired by lactic acidosis in melanoma patients, which has also been observed in breast cancer patients and mouse models." (PMID 39343933, 2024). "Wnt5a is an immunosuppressive molecule identified in the melanoma TME affecting pDC function." (PMID 39020402, 2024). "Interestingly, an increase in pDC recruitment was observed in BRAFV600E melanomas compared to BRAF wild-type melanomas." (PMID 39020402, 2024). "In general, the complete restoration of the pDC functions could be useful in melanoma’s treatment outcome." (PMID 38239354, 2023). "Altogether, these findings support the hypothesis that an increased lactic acidosis induced by high glycolytic tumor metabolism is involved in the melanoma-mediated pDC collapse." (PMID 32731406, 2020). "Notably, strong cytotoxic activities of pDC were observed, which were directed against ten of eleven melanoma cell lines, resulting in apoptotic and necrotic tumor cell death." (PMID 31083559, 2019). "The presence of CCR6+ pDC have been detected in primary melanoma tumors." (PMID 30420855, 2018). "It was shown in both ex vivo patient samples and in that a humanized melanoma mouse model that pDC in melanoma are directed toward a TH2 promoting phenotype by induction of the molecules OX-40L (TNFSF4) and ICOSL (inducible T cell costimulator ligand), which then drive tumor progression." (PMID 29276510, 2017). "Melanoma-associated pDCs have been shown to express high levels of IDO, suggesting that melanoma-derived signals may block pDC activation, thereby contributing to immune evasion." (PMID 29085361, 2017). "We observed significantly lower circulating pDC frequencies in stage IV melanoma patients." (PMID 25592374, 2015). "This study’s results indicate that, in some cancers like melanoma and lung cancer, these pDC–like cells might arise due to stiffness cues, while in other cancers like colon cancer other mechanisms might suppress the expression of pDC markers altogether." (PMID 39211033, 2024). "In principle, pDC are in a dormant stage in the vicinity of malignant melanoma lesions but, upon proper activation, may attack tumor cells via direct killer cell-like cytotoxic activity and/or may induce systemic adaptive immune responses against tumor-specific antigens." (PMID 31083559, 2019). "Moreover, given the negative prognostic value conveyed by tumor-infiltrating pDC in melanoma, CCR6 is likely to also be associated with poor patient outcome." (PMID 30420855, 2018). "Specifically, upon pDC activation, the IFN-α concentration measured by ELISA was significantly diminished after exposure to supernatants of melanoma cell lines." (PMID 38239354, 2023). "In human melanoma invaded lymph nodes and skin metastases, higher infiltration of the LAG3+ pDC subpopulation compared to blood was reported." (PMID 30987228, 2019). "We demonstrated that circulating pDC and MDSC levels are inversely correlated but have an independent prognostic value in melanoma patients." (PMID 25592374, 2015). "Moreover, melanoma cells express Wnt5a, which inhibits TLR-mediated pDC activation and IFN-I production." (PMID 29085361, 2017).
melanoma (continued). "However, interim results from a subsequent phase III trial (NCT02993315) evaluating combination pDC and cDC2 therapy in stage 3 melanoma demonstrated no improvement in 2-year RFS over placebo." (PMID 38903502, 2024). "pDC decline was the major negative prognosticator on OS and PFS in melanoma patients, independently of disease stage or frequency of other circulating cells." (PMID 32054102, 2020).
psoriasis (22 papers, 2012 to 2025). An autoimmune condition characterized by red, well-delineated plaques with silvery scales that are usually on the extensor surfaces and scalp. "It is reasonable to speculate the influence of genetic factors predisposing to paradoxical psoriasis, and specifically being involved in innate immunity pathways, in particular in pDC activation and/or type I IFN and TNF‐α signaling." (PMID 31577850, 2020). "Notably, CXXC5 is highly expressed in plasmacytoid dendritic cells (pDCs) and is crucial for robust interferon responses to TLR7/9 stimulation (pDCs are one of the initiating immune cell types in psoriasis, as self-DNA/RNA induced pDC activation has been implicated in psoriatic plaque development)." (PMID 41328434, 2025). "Innate immunity processes predominate in the early phase of psoriasis development, with pDC, neutrophils and mast cells being abundant in skin lesions." (PMID 38495872, 2024). "pDC recognize self-nucleic acids, thereby initiating inflammation of psoriasis through IFN-α production." (PMID 35837394, 2022). "The molecular players of pDC activation in psoriasis was getting characterized over the past decade." (PMID 35207521, 2022). "The antimicrobial peptide, LL37, binds DNA to form a coil-node structure and subsequently mediates pDC activation and drives autoimmunity in psoriasis." (PMID 33841441, 2021). "Interestingly, Zdhhc2 deficiency mice exhibited significantly lower frequency and count of pDC than the WT mice, indicating that loss of Zdhhc2 potently inhibits the infiltration of pDC to organs, especially the skin, thereby reducing the incidence of psoriasis." (PMID 33488612, 2020). "And other research have shown that pDC plays an important role in initiating psoriasis through interferon-alpha production." (PMID 33488612, 2020). "In conclusion, our study identified the critical role of Zdhhc2 in development of psoriasis and pDC accumulation in the skin and we found that IFN-α production was completely dependent on Zdhhc2." (PMID 33488612, 2020). "For example, increased expression of TLRs has been observed in peripheral B cells from patients with inflammatory bowel disease, while recognition of self-DNA complexes by TLR9 mediates pDC activation in psoriasis." (PMID 28744288, 2017). "For example, recognition of self-DNA/protein complexes by TLR9 mediates pDC activation in psoriasis, breaking self-immune tolerance." (PMID 28744288, 2017). "While in early and developing psoriasis the role of pDC seems clear, a role in more chronic psoriasis is less distinct." (PMID 24744755, 2014). "In psoriasis patients, pDC migrate into the skin, where they sense self-DNA and produce type-I IFN thereby accelerating the disease." (PMID 22952871, 2012). "In addition, circulating pDC numbers in psoriasis patients are generally reduced due to their migration into inflamed skin lesions." (PMID 41303461, 2025). "Of note, AMPs are overexpressed in psoriasis and, consequently, pDC activation is sustained." (PMID 35207521, 2022). "Notably, pDC accumulation coincides with elevated type I IFN expression at a uniform rate regardless of the clinical or histological phenotype in paradoxical psoriasis." (PMID 29295985, 2018). "Thus, although pDC are necessary for the initiation of psoriasis, the specific role of other skin-resident DC subsets in the attenuation or exacerbation of psoriasis largely remains elusive." (PMID 26229971, 2015). "Indeed, when corresponding pDC to phases of psoriasis, pDC are especially found in early and developing psoriasis, and hardly in chronic psoriasis." (PMID 24744755, 2014). "Thus, the agents that activate the circulating pDC of patients with psoriasis may be different from those that are present in skin." (PMID 31539532, 2020).